CBLC (Cbl proto-oncogene C)
Diseases named in the same sentence as CBLC in open-access papers (continued):
Sharing a sentence is not in itself a finding about the gene and the disease.
nephrotic syndrome (3 papers, 2022 to 2024). A collection of symptoms that include severe edema, proteinuria, and hypoalbuminemia; it is indicative of renal dysfunction. "Group 1 was characterized by major risk genes for developing LOAD (APOC1 and APOC1P1) and immune-related genes (RELB and CBLC), whereas group 2 was characterized by genes associated with kidney disorders, such as nephrotic syndrome (AXDND1, FBP1, and MIR2278)." (PMID 37386009, 2023). "While cblC defects are more commonly associated with atypical hemolytic uremic syndrome, this case highlights the importance of considering cobalamin defects in the differential diagnosis of nephrotic syndrome, especially when associated with accompanying findings such as hemolysis." (PMID 38977946, 2024). "This case underscores the significance of recognizing metabolic disorders like cblC defect in atypical presentations of nephrotic syndrome." (PMID 38977946, 2024). "In conclusion, this case underscores the importance of considering metabolic disorders such as cblC defect in the differential diagnosis of nephrotic syndrome, particularly in cases with atypical or severe presentations." (PMID 38977946, 2024). "In this case report, we present a rare and intriguing clinical scenario of a patient with nephrotic syndrome, malign hypertension hemolytic anemia attributed to Cobalamin C (cblC) defect." (PMID 38977946, 2024). "The long-term prognosis of nephrotic syndrome in cblC defect is variable and often depends on the extent of renal involvement and the promptness of treatment initiation." (PMID 38977946, 2024). "The management of cblC defect with nephrotic syndrome is multifaceted and challenging." (PMID 38977946, 2024). "Renal manifestations including thrombotic microangiopathy (TMA), atypical hemolytic uremic syndrome (aHUS), and nephrotic syndrome have been described in cblC deficiency, and MMACHC variant c.271dupA was the most frequent damaged allele in patients with cblC defect and renal TMA." (PMID 36704130, 2022).
organic acidemia (3 papers, 2019 to 2025). "cblC deficiency is the most common disorder of organic acidemia in China, while PH as a leading symptom is rare and these cases have mainly been presented with case reports." (PMID 40468431, 2025). "Methylmalonic acidemia (MMA) is the most common organic acidemia in China, with cblC (cblC-MMA) and mut (mut-MMA) being the predominant subtypes." (PMID 39306609, 2024).
pulmonary hypertension (3 papers, 2017 to 2025). Increased pressure within the pulmonary circulation due to lung or heart disorder. "Pulmonary Hypertension (PH) in patients with cblC deficiency is one of the rare but lethal complications." (PMID 40468431, 2025). "Interstitial lung disease was reported as a serious AE in a 2-year-old cblC-defective male patient treated with betaine anhydrous (2 g/day) who experienced respiratory distress related to pulmonary hypertension and interstitial lung disease leading to death." (PMID 30871635, 2019). "The concept of cardiorenal syndrome with pulmonary hypertension and TMA in MMACHC deficiency is supported by hemolytic anemia in an infant with cblC defect who died from cor pulmonale and by increased creatinine and LDH levels in another infant who died from pulmonary hypertension and MMACHC." (PMID 27289364, 2017).
cognitive decline (2 papers, 2023 to 2025). "Overall, cognitive decline and motor involvement were dominant symptoms, while ocular involvement seems to be rare in late-onset cblC defect." (PMID 37770946, 2023).
Cognitive impairment (2 papers, 2022 to 2025). Abnormal cognition is characterized by deficits in thinking, reasoning, or remembering. "In this study, we found the levels of methylmalonic acid in the serum total exosomes reflected the cognitive impairment induced by cblC-MMA more accurately than total methylmalonic acid in the serum." (PMID 36582607, 2022). "Methylmalonic acid levels in serum exosomes, especially in serum neuronal-derived exosomes, serve as potential biomarkers for distinguishing cblC-MMA induced cognitive impairment." (PMID 36582607, 2022). "In this study, we aimed to clarify the roles of these biomarkers in cblC-MMA induced cognitive impairment and evaluate the capacity of methylmalonic acid in different fluids or exosomes to distinguish cblC-MMA induced cognitive impairment." (PMID 36582607, 2022). "In addition, compare to cblC-MMA patients with normal cognition, the levels of methylmalonic acid in serum total exosomes and neuro-exosomes of the cblC-MMA patients with cognitive impairment significantly increased." (PMID 36582607, 2022). "The methylmalonic acid in neuronal-derived exosomes might be helpful to evaluate the severity of cblC-MMA induced cognitive impairment." (PMID 36582607, 2022). "Especially, serum neuronal-derived exosomes reflected pathological changes in the brain of cblC-MMA patients, which should serve as a potential biomarker for estimating the severity of MMA-induced cognitive impairment." (PMID 36582607, 2022). "In cblC-MMA cases, serum exosomal MMA levels, particularly in neuron-derived exosomes, may serve as biomarkers for identifying MMA-induced cognitive impairment." (PMID 40635714, 2025). "Then, we found non-inherited HHcy patients were not trouble with cognitive impairment, but the serum homocysteine and acylcarnitine biomarkers of non-inherited HHcy patients had similar elevated trends with cblC-MMA patients." (PMID 36582607, 2022). "More importantly, the methylmalonic acid in serum exosomes had the capacity to differentiate cblC-MMA patients with or without cognitive impairment." (PMID 36582607, 2022). "The levels of methylmalonic acid in serum total exosomes and in serum neuro-exosomes showed better performance than serum homocysteine, methylmalonic acid in the urine and in the serum for distinguishing cblC-MMA patients with or without cognitive impairment." (PMID 36582607, 2022).
epilepsy (2 papers, 2024 to 2025). A brain disorder characterized by episodes of abnormally increased neuronal discharge resulting in transient episodes of sensory or motor neurological dysfunction, or psychic dysfunction. "One patient (P8) with cblC deficiency, presented with epilepsy and unstable walking." (PMID 40994713, 2025).
prostate carcinoma (2 papers, 2012 to 2023). A carcinoma that arises from epithelial cells of the prostate gland. "Our data have thereby identified CBLC as a novel promoter of prostate cancer and to be potentially one of the seminal genes regulated by methylated JMJD2D." (PMID 38045004, 2023). "Consistently, we observed that CBLC downregulation phenocopied the anti-oncogenic effects of the R427 mutation in DU145 cells, establishing for the first time that CBLC exerts tumor promoting activities in prostate cancer cells." (PMID 38045004, 2023). "This would be consistent with the notion that methylation of JMJD2D could promote prostate cancer development through upregulation of CBLC and METTL27 as well as through downregulation of COL4A5, GLIS3, NPR1, OSR2, PLAGL1 and RSPO3." (PMID 38045004, 2023). "This included downregulation of CBLC, a ubiquitin ligase gene with hitherto unknown functions in prostate cancer, and upregulation of PLAGL1, a transcription factor with reported tumor suppressive characteristics in the prostate." (PMID 38045004, 2023). "Our interest was particularly piqued by CBLC (cbl proto-oncogene C) since it is robustly expressed in normal prostate tissue, yet its relationship with prostate cancer has remained unknown." (PMID 38045004, 2023).
refractory anemia (2 papers, 2017 to 2019). "Mutations in genes other than PIGA, EGFR-AS1, AKT2 and CBLC, were largely distributed in subjects with refractory anemia with excess blasts (RAEB) (n = 56) or the AML with multilineage dysplasia following MDS (MDS-AML) (n = 24)." (PMID 29137279, 2017).
adrenoleukodystrophy (1 paper, 2020). A peroxisomal disorder resulting in cerebral demyelination, axonal dysfunction in the spinal cord leading to spastic paraplegia, adrenal insufficiency and in some cases testicular insufficiency. "In inherited metabolic diseases, spinal cord involvement is most frequently reported in adrenoleukodystrophy, biotinidase deficiency, arginase deficiency, and cobalamin-related remethylation disorders cblC, cblD, cblE, cblF, cblG, cblJ, and MTHFR deficiency." (PMID 33520891, 2020).
anemia (1 paper, 2024). A reduction in the number of red blood cells, the amount of hemoglobin, and/or the volume of packed red blood cells. "However, for cblC-MMA patients and symptoms like death, ocular complications and anemia, the differences and diagnostic value were inconclusive." (PMID 39306609, 2024). "For cblC-MMA patients, multivariate analysis revealed that “pre-treatment onset” (OR = 8.62–26.7) and “NBS” (OR = 0.03–0.42) were independent predictors of nearly all analyzed poor prognostic manifestations except death and anemia." (PMID 39306609, 2024).
Brain atrophy (1 paper, 2017). Partial or complete wasting (loss) of brain tissue that was once present. "A polygenic risk score of all rare variants in 3 genes (CBLC, BCAM, RELB) was associated with multifocal brain atrophy, predominantly in the temporal and bilateral frontal lobes." (PMID 28589856, 2017).
cerebellar ataxia (1 paper, 2023). A neurological syndrome characterized by clumsy and uncoordinated movement of the limbs, trunk, and cranial muscles. "In this report, we present a case of late-onset cblC deficiency in adults presenting with cerebellar ataxia as the primary symptom." (PMID 38148982, 2023).
Cerebellar atrophy (1 paper, 2022). Cerebellar atrophy is defined as a cerebellum with initially normal structures, in a posterior fossa with normal size, which displays enlarged fissures (interfolial spaces) in comparison to the foliae secondary to loss of tissue. "CblC defects with cerebellar atrophy, corpus callosum thinning and ventricular dilation had significantly lower DQs than those without (P < 0.05)." (PMID 36590295, 2022). "Furthermore, we found that the DQ of cblC defect patients with cerebellar atrophy, thinned corpus callosum, and ventricular dilation was significantly decreased." (PMID 36590295, 2022).
Cerebral atrophy (1 paper, 2023). Atrophy (wasting, decrease in size of cells or tissue) affecting the cerebrum. "In our study, cerebral atrophy, periventricular white matter abnormality, ventricular dilation and sulcal widening were the main findings in patients with cblC defect, which was correlated with previously published literature." (PMID 37770946, 2023).
chronic kidney disease (1 paper, 2023). Impairment of the renal function secondary to chronic kidney damage persisting for three or more months. "In adults, cblC deficiency may present with proteinuria, hypertension, chronic kidney disease (CKD), and aHUS." (PMID 38201964, 2023).
dissection (1 paper, 2024). The separation and isolation of tissues for surgical purposes, or for the analysis or study of their structures. "This is the first study to depict a case of cblC deficiency with aortic dissection as a presenting sign." (PMID 38178022, 2024). "This case is the first to depict a case of adult-onset cblC deficiency with aortic dissection." (PMID 38178022, 2024).
hyperlipidemia (1 paper, 2023).
hyperopia (1 paper, 2021). A refractive error in which rays of light entering the eye parallel to the optic axis are brought to a focus behind the retina, as a result of the eyeball being too short from front to back. "Except for hyperopia she has no signs and symptoms of cblC deficiency." (PMID 33980297, 2021).
kidney damage (1 paper, 2022). "Children with cblC deficiency who manifested as kidney damage were enrolled." (PMID 36704130, 2022).
non-compaction cardiomyopathy (1 paper, 2025). Left ventricular non-compaction (LVNC) is characterized by prominent left ventricular trabeculae and deep inter-trabecular recesses. "The fact that number of other cblC patients have been reported to have non compaction cardiomyopathy supports the hypothesis of a specific association between cblC and cardiac pathology; defective intracellular cobalamin metabolism might impair myocyte differentiation and myocardial maturation." (PMID 40276563, 2025).
prostate tumors (1 paper, 2023). "Bioinformatic analyses indicated that CBLC expression was elevated in prostate tumors." (PMID 38045004, 2023).
sarcoma (1 paper, 2019). A usually aggressive malignant neoplasm of the soft tissue or bone. "We next examined the expression of 19 genes in different bone-related sarcomas using The Cancer Genome Atlas (TCGA) database and found relatively high HSPA5 and ATF4 mRNA levels in tumor tissues and significantly low CBLC and RET expression levels." (PMID 31534554, 2019).
Stroke (1 paper, 2018). Sudden impairment of blood flow to a part of the brain due to occlusion or rupture of an artery to the brain. "The functional roles of CBLC in stroke-susceptibility in SHRSP and the functional importance of the variations inside this gene should be evaluated in future studies." (PMID 29925869, 2018).
cancer (19 papers, 2013 to 2025). A tumor composed of atypical neoplastic, often pleomorphic cells that invade other tissues. "In conclusion, our results show that epi-cblC should be distinguished from cblC, with potential consequences on spermatogenesis and cancer risk produced by TESK2 silencing." (PMID 35440018, 2022). "Of these, several are found in genes involved in DNA damage response and double-strand DNA repair mechanisms, including MCL1, ATR, KMT2C, and CBLC, indicating genomic instability and cancer predisposition." (PMID 34299215, 2021). "In other cancer contexts, Cbl proto-oncogene C (CBLC) combines with IGF-1R and mediates receptor polyubiquitination in response to IGF-1." (PMID 30111747, 2018). "A corollary is that JMJD2D and CBLC inhibitors could have therapeutic benefits in the treatment of prostate and possibly other cancers." (PMID 38045004, 2023). "CBLC might be involved in the development of GBM because it is a cancer gene and is contained in the ERBB signaling pathway, an important GBM-related pathway that includes four GBM genes in this module." (PMID 25611546, 2015). "CBLC belongs to the CBL family and is an E3 ubiquitin ligase involved in EGFR ubiquitination and degradation, widely upregulated in various cancers, including NSCLC, hinting at its oncogenic potential." (PMID 40766337, 2025). "Another example is Cbl Proto-Oncogene C (CBLC), which has evidence of interacting with the major oncogenes, EGFR and ERBB241, and was highly expressed in 12 cancer types at transcriptomic and proteomic levels, and lowly expressed in most normal tissues." (PMID 37845222, 2023).
tumor (18 papers, 2015 to 2025). "The CBLC gene, affected by a non-synonymous mutation (c.1174G > A), is known to influence tumor suppression, cell cycle regulation, proliferation, and DNA repair." (PMID 40486961, 2025). "As a result, genes encoding ubiquitin conjugating enzymes or ligases, such as UBE2T, UBE2C, and CBLC, were up‐regulated in tumor tissues, while genes encoding deubiquitinating enzymes like OTUD1 and USP12 were down‐regulated." (PMID 37983609, 2024). "It is therefore plausible that transcriptional, translational or proteolytic suppression of CBLC in tumours might be a more common event than gene mutations." (PMID 25883215, 2015). "As these kinases are proto-oncoproteins, CBLC may serve a tumor suppressive function similar to its close homologs, CBL and CBLB." (PMID 38045004, 2023). "Whether in Oncomine or in UALCAN, ADRB2, ARRB1, BDNF, etc., had a lower expression in tumor group than normal tissues, whereas CBLC, GPI, and PAK1 had a higher expression in tumor group than normal tissues." (PMID 35833114, 2022). "The role that CBLC plays in DNA repair by homologous recombination, described here, might suggest that this ubiquitin ligase could represent a candidate for a novel tumour suppressor." (PMID 25883215, 2015). "In LUAD studies, WGCNA combined with immune-related genes identified four key hub genes: CBLC, FABP4, GDF10, and LTBP4, showing significant differential expression between tumor and normal samples." (PMID 40766337, 2025). "ADRB2, ANGPTL4, BDNF, CBLC, CX3CR1, and IL3RA were found markedly different expression between the tumor and normal group." (PMID 35833114, 2022). "CBLC is significantly upregulated in LUAD, especially in patients with poor prognosis, suggesting that it may promote tumor invasion." (PMID 40766337, 2025). "Tumor-infiltrating PDCD1+ and LAG3+ cells expressed CBLB, while a minor proportion expressed CBLC." (PMID 39030301, 2024). "Moreover, we ascertained that the different expression of ADRB2, ANGPTL4, BDNF, CBLC, CX3CR1, and IL3RA in tumor and normal group was consistent both in PCR and UALCAN." (PMID 35833114, 2022).
metabolic disease (5 papers, 2019 to 2024). A congenital disorder (due to inherited enzyme abnormality) or acquired (due to failure of a metabolically important organ) disorder resulting from an abnormal metabolic process. "it is essential for clinicians to be aware of its diverse etiologies, including rare metabolic disorders like cblC defect." (PMID 38977946, 2024). "We suggest that women with late-onset cblC defect can have a positive pregnancy outcome if this metabolic disease is treated adequately." (PMID 31470807, 2019).
renal disease (3 papers, 2017 to 2023). "HUS and renal pathology characterized by TMA were the most frequent manifestations of cblC defect-associated renal disease, and the age of onset varied from the neonatal to adult stage." (PMID 36704130, 2022). "To enhance awareness and understanding of renal disease associated with cblC defect, we studied biochemical, genetic, clinical, and histopathological data from 36 patients." (PMID 27289364, 2017). "This study aimed to better delineate cblC-associated renal disease and the genotypes." (PMID 36704130, 2022). "Furthermore, the renal pathology of patient 1, undergoing in 1 month after onset, revealed chronic TMA lesions such as duplication of the glomerular basement membrane and vascular onion-skin hyperplasia, which demonstrated the insidious onset of cblC-associated renal disease." (PMID 36704130, 2022). "Therefore, we speculated that Chinese dominant cblC-associated renal disease might be highly associated with MMACHC pathogenic variant c.80A > G." (PMID 36704130, 2022). "On the other hand, renal disease in four of seven patients completely resolved, providing evidence for the importance of timely identification and specific therapy of cblC defect." (PMID 36704130, 2022). "However, renal involvement as the initial symptom of cblC deficiency is not common, and both plasma homocysteine and urine methylmalonic acid are not routinely measured; thus, cblC-associated renal disease is frequently misdiagnosed." (PMID 36704130, 2022).
cardiovascular disease (1 paper, 2025). "Despite the limitations of this study, our observations support the importance of cardiac screening in IMDs with a significant risk of cardiovascular disease, including GSD III, CblC, PA, MELAS, and KSS." (PMID 40276563, 2025).